AKT2 (AKT serine/threonine kinase 2)
Diseases named in the same sentence as AKT2 in open-access papers (continued):
Sharing a sentence is not in itself a finding about the gene and the disease.
melanoma (18 papers, 2008 to 2025). A malignant, usually aggressive tumor composed of atypical, neoplastic melanocytes. "For example, upon the loss of PTEN, the invasiveness of human melanoma cell lines was enhanced through the preferential phosphorylation of AKT2, whereas AKT3 phosphorylation reduced the invasive potential of PTEN-null melanoma cells." (PMID 37894325, 2023). "Our xenograft studies suggest that PTEN-deficient melanomas are initially sensitive to AKT2 inhibition but ultimately do not depend on AKT2 over the long term, given our observation of delayed tumor outgrowth in the AKT2 knockdown mice, as well as unmitigated tumor growth of AKT2 KO cells." (PMID 37894325, 2023). "Moreover, both AKT1 and AKT2 have been implicated in melanoma metastasis." (PMID 35158840, 2022). "Consistently, the Akt2 splicing switch from Akt2-210 to Akt2-201 in MAPKi-treated mouse model recapitulates the splicing pattern mediating A-loop restoration observed in melanoma patients." (PMID 40681872, 2025). "Functional validations confirm that AKT2-206 confers BRAF inhibitor resistance in melanoma cells by activating S6 kinase." (PMID 40681872, 2025). "Given the pivotal role of AKT in both the MAPK and PI3K-AKT signaling pathways, we validated the biological function of the identified AKT2 isoforms regarding conferring MAPKi resistance in melanoma." (PMID 40681872, 2025). "We further show that while AKT2 is dispensable for melanoma initiation, AKT1 contributes to BRAF-driven murine melanoma initiation and cell proliferation, which is in line with our previous results." (PMID 37894325, 2023). "In summary, by using genetically engineered human cell lines and novel syngeneic mouse models, we reveal multiple roles for AKT2 in melanoma metastasis." (PMID 37894325, 2023). "When taken together, these data suggest that AKT2 depletion in vitro impairs the functions required for melanoma metastasis, such as migration and invasion." (PMID 37894325, 2023). "In order to study AKT2 in the context of metastatic murine melanoma, we generated an aggressive murine melanoma cell line, SM1-750, which exhibits high metastatic potential." (PMID 37894325, 2023). "We further investigate AKT isoform phosphorylation in primary spontaneous murine melanomas and human metastatic melanoma cell lines, finding that AKT2 phosphorylation specifically increases in metastatic lesions." (PMID 37894325, 2023). "Further, invasion through Matrigel was impaired by AKT2 depletion in the same human melanoma cell lines." (PMID 37894325, 2023). "Together, these results strongly suggest that selective AKT2 knockdown inhibits glycolysis in WM1799 human melanoma cells." (PMID 37894325, 2023). "The preceding data suggest that AKT2 differentially promotes the metastatic potential of melanomas, but to address the mechanism, we utilized a set of human melanoma cell lines driven by mutation in BRAF, as well as by PTEN loss." (PMID 37894325, 2023). "AKT2-specific roles in maintaining glucose homeostasis are well-documented, and metabolic rewiring in melanoma can facilitate metastatic dissemination." (PMID 37894325, 2023). "Despite the apparent inability of AKT1 to fully support metastasis in AKT2-depleted human melanoma cells, hyperactive AKT1 contributes to the metastatic potential of the mouse SM1-750 model." (PMID 37894325, 2023). "We found that AKT2 specifically regulates melanoma cell metastasis through effects on metabolism and melanoma cell properties, while AKT1 is involved in cellular proliferation and growth." (PMID 37894325, 2023). "This is in line with our data showing only strong AKT1 phosphorylation in primary mouse tumors, distinguishing the role of AKT2 in metastatic seeding from the role of AKT1 in primary murine melanoma formation." (PMID 37894325, 2023). "Since AKT2-G161V was found in a human melanoma sample, we explored the pro-survival potential of this mutant in immortalized human melanocytes." (PMID 25551293, 2014).
melanoma (continued). "Here, we employ inducible AKT-isoform-specific shRNAs and CRISPR/Cas9-mediated gene editing in human melanoma cell lines to outline the role of AKT2 in the metastatic cell seeding of oncogenic BRAF-driven PTEN-null melanoma through the enhancement of cell migration and invasiveness." (PMID 37894325, 2023). "Our data suggest that the elucidation of AKT2-specific functions in metastasis might inform therapeutic strategies to improve treatment options for melanoma patients." (PMID 37894325, 2023). "We observed that AKT1 loss extended overall survival in melanoma-prone mice, while AKT2 and AKT3 loss did not." (PMID 37894325, 2023). "Additionally, only AKT2 knockdown decreased the expression of TEA domain (TEAD) genes, which are invasion-associated genes previously implicated in melanoma metastasis." (PMID 37894325, 2023). "By contrast, even though mutations in the catalytic subunit of PI3K, or AKT1, AKT2, and AKT3, are rare in melanoma, immunopositivity of AKT3 is common in melanoma, and could activate PI3K–AKT–mTOR in PTEN wild type tumors." (PMID 36135270, 2022). "Furthermore, siRNA knockdown of GRM1 in human melanoma cell also resulted in a decrease in AKT2 phosphorylation corroborating that AKT2 is a downstream target of GRM1." (PMID 23372575, 2012). "AKT2 over-activation has also been identified in melanoma, breast, and ovarian cancer." (PMID 23372575, 2012). "The splicing factor hnRNPK drives a splicing switch of AKT2 (isoform 210 to 206), restoring kinase hyperactivity via retention of the A-loop fragment and conferring MAPK-targeted therapy resistance in melanoma through PI3K-AKT pathway activation." (PMID 40681872, 2025). "This study suggests that specifically targeting AKT2 and AKT1 represents novel therapeutic strategies for different-stage melanoma patients." (PMID 37894325, 2023). "Upon examining the new attention map post the removal of high-attention genes, we discern that the model now places more attention on genes HRAS, AKT2, PIK3CA for melanoma." (PMID 37932419, 2023). "Our data support an isoform-specific role for AKT2 in melanoma metastasis, with a shared role for AKT1 and AKT2 in tumorigenesis." (PMID 37894325, 2023). "We propose a mechanism whereby the inhibition of AKT2 impairs glycolysis and reduces an EMT-related gene expression signature in PTEN-null BRAF-mutant human melanoma cells to limit metastatic spread." (PMID 37894325, 2023). "In melanoma, AKT1 and AKT2 activation are more commonly found in BRAF-mutant tumors, while AKT3 hyperactivity is more common in BRAF wild-type melanomas." (PMID 35158840, 2022). "Using isoform-specific guide RNAs (gRNAs), we used CRISPR-Cas9 to knockout AKT1, AKT2, or AKT3 in multiple melanoma cell lines, validating the success of AKT knockout by Western blotting." (PMID 35158840, 2022). "ASO-mediated silencing of exon 10 significantly increased the sensitivity of melanoma cells to PLX4032, suggesting that targeting AKT2 splicing might represent a strategy to overcome MAPKi resistance." (PMID 40681872, 2025). "We elucidate that AKT2 is dispensable for primary tumor formation but promotes migration and invasion in vitro and metastatic seeding in vivo, whereas AKT1 is uniquely important for melanoma initiation and cell proliferation." (PMID 37894325, 2023). "This is also consistent with our observation that tumor-derived cell lines consistently show robust phosphorylation of AKT1 when compared with other AKT isoforms, suggesting that AKT1 but not AKT2 or AKT3 plays a critical role in melanoma initiation." (PMID 37894325, 2023). "AKT2 and AKT3 have emerged as the predominant forms that are dysregulated in melanoma." (PMID 23372575, 2012). "Strikingly, 5.00% (2/40) of advanced melanomas exhibited upregulated AKT2-206 expression in the absence of established resistance drivers, suggesting that it may serve as an independent resistance mechanism in molecularly distinct patient subgroups." (PMID 40681872, 2025).
melanoma (continued). "Similarly, it has been shown that the PHLPP1 phosphatase suppressed melanoma metastasis through the dephosphorylation of AKT2 or AKT3 but not AKT1 in human melanoma cells." (PMID 37894325, 2023). "In order to determine whether AKT2 is important for the process of metastatic seeding and metastatic nodule growth, we performed a tail vein metastasis assay in which WM1799 shAKT2-Luc melanoma cells were allowed to seed the lungs." (PMID 37894325, 2023). "In contrast, when the effects of Akt inhibitors on anoikis of the melanoma cells were compared, the Akt2 isoform demonstrated a non-canonical activity in which Akt2 suppression led to a significant attenuation of apoptosis in cells with downregulated α3β1 or α5β1." (PMID 33260159, 2020). "In addition, in 1205LU melanoma cell lines expressing ShRUNX2-3, phosphorylation of AKT2 at S474 was decreased as compared with the non-silencing control-expressing 1205LU cells." (PMID 27102439, 2016). "Indeed, as AKTs are central pleiotropic signaling hubs, it is not surprising that the AKT2-mediated cellular changes facilitating melanoma metastasis are manifold, including glycolytic changes and the enhancement of factors promoting epithelial-to-mesenchymal transition." (PMID 37894325, 2023). "By using a conventional in vitro wound healing assay, it was found that only AKT2 depletion and not AKT1 or AKT3 depletion inhibited cell migration in three different human melanoma cell lines." (PMID 37894325, 2023). "Overall, our findings are consistent with a role for AKT2 in the regulation of not just EMT but also glycolytic versus aerobic respiration, promoting melanoma invasiveness and metastatic activity." (PMID 37894325, 2023). "In order to investigate why AKT1 but not AKT2 impaired primary tumor growth, we analyzed cellular proliferation in our inducible AKT1 and AKT2 knockdown melanoma cell lines." (PMID 37894325, 2023). "In BrafV600E-driven murine melanomas lacking Cdkn2a, AKT1 activation was shown to enhance brain metastasis, whereas AKT2 and AKT3 had a less pronounced effect." (PMID 37894325, 2023). "Gene expression analysis identified activation of AKT3, but not AKT1 or AKT2, as a major cell survival node upregulated in CD271+ melanoma-initiating cells." (PMID 31118427, 2019). "An AKT kinase domain mutant found in human melanoma (G161V) lacked enzymatic activity in vitro and in AKT1/AKT2 double knockout cells, but promoted growth factor independent survival of primary human melanocytes." (PMID 25551293, 2014). "Nevertheless, our finding that AKT2 knockdown greatly attenuates the metastatic potential of human melanoma cell lines is consistent with previous data, suggesting that PHLPP1 inhibits melanoma metastasis by suppressing the phosphorylation of AKT2 and AKT3 but not AKT1." (PMID 37894325, 2023). "Notably, melanoma and tumours arising in liver, eye and bone showed weak correlation between USP28 and AKT2‐BRAF, and for thyroid cancer, we observed a negative correlation." (PMID 35364627, 2022).
lipodystrophy (17 papers, 2012 to 2025). A congenital or acquired disorder characterized by abnormal loss or redistribution of the adipose tissue in the body. "One proband reporting previously with the loss-of-function p.Arg274His mutation in AKT2 showed femorogluteal lipodystrophy, whereas both patients whom we describe at 17 years old were obese." (PMID 28541532, 2017). "This raises the possibility that AKT2 is more important for insulin action in adipocytes than in hepatocytes, so that partial loss of its function is expressed as a predominantly “lipodystrophy-like” metabolic phenotype." (PMID 27766312, 2016). "Moreover, AT also partially reversed lipodystrophy-induced inhibition of insulin sensitivity-associated gene expression in both the livers (Irs2 and Akt2) and the skeletal muscles (Akt2) of Seipin/Apoe dKO mice." (PMID 38525541, 2024). "Mutations in PI3K and akt2 genes have also been implicated in lipodystrophy in humans." (PMID 34639094, 2021). "Notably, rare loss-of-function AKT2 mutations in humans are associated with partial lipodystrophy and severe insulin resistance." (PMID 32493999, 2020). "Mutations in several genes have been found in patients with inherited lipodystrophies, including mutations in LMNA, PPARG, AKT2 and ZMPSTE24 in partial lipodystrophy, and mutations in AGPAT2, BSCL2, CAV1 and PTRF in congenital total lipodystrophy." (PMID 26987365, 2016). "siRNA designed to restore AKT2 function could enhance both adipogenesis and insulin sensitivity, which is crucial for managing the metabolic aspects of lipodystrophy." (PMID 39944202, 2025). "In addition, Akt1/Akt2-DKO mice have dyslipogenesis, and AKT deficiency in adipocytes can lead to severe lipodystrophy." (PMID 33633792, 2021). "In addition, the presence of partial lipodystrophy seen in AKT2 highlights the importance of AKT2 in adipocyte differentiation as well as its role in the direct effects of insulin signaling." (PMID 23766565, 2013). "On the other hand, the fact that adipocyte-specific deletion of AKT2 does not impair glucose tolerance whereas insulin receptor deletion does, and given that lipodystrophy is similarly severe in both mice, is quite unexpected." (PMID 35250856, 2022). "First, we were not able to search for another mutations linked to lipodystrophy phenotypes (PPARG, AKT2, and PLIN1)." (PMID 22938045, 2012). "Notably, while many previously known lipodystrophy genes fell within the “lipocluster”, several did not (e.g., CAV1, PTRF, AKT2, CIDEC, LMNA)." (PMID 30940487, 2019).
thyroid cancer (14 papers, 2014 to 2025). "Compared with the regions of normal surrounding thyroid tissue, a notable increase in the expression of phosphorylated Akt, Akt1, and Akt2 was observed in the regions of HT and thyroid cancer." (PMID 40364944, 2025). "Other reports have shown INPP4B is enriched on early endosomes of thyroid cancer cells, where it suppressed localized AKT2 activation." (PMID 34035258, 2021). "While all three Akt isoforms regulate thyroid growth, Akt1 is the primary promoter of thyroid cancer development and local invasion, while vascular invasion and metastatic progression are dependent on Akt1 and 3, and to a lesser extent Akt2." (PMID 33110146, 2020). "Spearman’s correlation analysis demonstrated that the mRNA levels of AKT2 expression in thyroid carcinoma tissues were inversely correlated with let-7a expression levels (Spearman’s correlation r=-0.4716, p<0.05)." (PMID 29050238, 2017). "Larson found that PI3K pathway - the key pathway of tumor progression especially in phosphorylated Akt, Akt1 and Akt2, was expressed in thyroid cancer and Hashimoto’s thyroiditis, but not in normal thyroid tissues." (PMID 34993154, 2021). "For example, depletion of INPP4B selectively activates AKT2 but not AKT1 in the endosomes of thyroid cancer cells." (PMID 30012111, 2018).
bladder cancer (13 papers, 2012 to 2023). "Also, a Caucasian study showed that AKT2 variant rs3730050 was associated with poor prognosis of bladder cancer patients." (PMID 28977864, 2017). "In bladder cancer cell lines, it was observed that curcumin up-regulated the expression of miR-203 and in turn decreased the expression of AKT2 and SRC." (PMID 33292283, 2020). "Collectively, these data suggest that miR-148a-3p/ERBB3/AKT2/c-myc establishes a positive feedback loop in bladder cancer regulation, indicating that miR-148a-3p is a promising therapeutic target." (PMID 27906180, 2016). "Collectively, these data indicate that miR-148a-3p/ERBB3/AKT2/c-myc establish a positive feedback loop in bladder cancer regulation." (PMID 27906180, 2016). "In parallel, the colony-forming ability of bladder cancer cells decreased, as the colony formation capacity of Si-AKT2-transfected cells was much worse than that of cells transfected with NC." (PMID 27906180, 2016). "Induced expression of miR-203 led to the down-regulation of Akt2 and Src, as well as a decreased rate of proliferation, and an increase in apoptosis of bladder cancer cells." (PMID 23863690, 2013). "In bladder cancer, miR-203 was demonstrated to suppress tumors by directly targeting Akt2/Src and Bcl-w." (PMID 23863690, 2013). "For instance, miR-203 reduces p63 in skin differentiation, and Akt2, Src, c-jun, survivin and bcl-w in bladder cancer." (PMID 23285092, 2012). "This led to downregulation of miR-203 target genes Akt2 and Src resulting in decreased proliferation and increased apoptosis in bladder cancer cells." (PMID 22449094, 2012). "Down-regulation of the Akt2 and Src promoted apoptosis in bladder cancer cells." (PMID 33292283, 2020). "Furthermore, the miR-148a-3p/ERBB3/AKT2/c-myc signaling axis establishes a positive feedback loop in the regulation of bladder cancer." (PMID 27906180, 2016). "Therefore, targeting the miR-148a-3p/ERBB3/AKT2/c-myc regulatory circuit may be a novel strategy for the treatment of bladder cancer." (PMID 27906180, 2016). "Data identified that in the low HER2 cohort and different ATM levels (high/low); ABL1, SMAD4, RB1 and PARP1 were significantly upregulated and AKT1, AKT2, TSC2, RPTOR and mTOR were significantly downregulated in bladder cancer." (PMID 36056635, 2022). "MiR-148a has been shown to inhibit cell proliferation and EMT properties in bladder cancer through ERBB3/AKT2/c-myc and ERBB3/AKT2/Snail signaling." (PMID 30944375, 2019). "A total of nine chr3p25 and chr11p11 genes were functionally connected to genes in the KEGG bladder cancer pathway (E2F1, E2F3, EGFR, RAF1, RB1) or to other cancer-related genes (AKT2, PIK3CA, RB1, TRIO)." (PMID 29140994, 2017). "We demonstrated novel regulatory circuits involving miR-148a-3p/ERBB3/AKT2/c-myc and DNMT1 that controlled bladder cancer progression." (PMID 27906180, 2016). "miR-148a-3p inhibits bladder cancer cell proliferation and epithelial–mesenchymal transition (EMT) by regulating ERBB3/AKT2/c-myc and ERBB3/AKT2/Snail signaling." (PMID 27906180, 2016). "Our study identified regulatory loops between miR-148a-3p/ERBB3/AKT2/c-myc and DNMT1 in bladder cancer regulation, which could prove useful in the development of effective and therapies against bladder cancer." (PMID 27906180, 2016). "Furthermore, we identified novel regulatory circuits involving miR-148a-3p/ERBB3/AKT2/c-myc and DNA methyltransferase 1 (DNMT1) in the control of bladder cancer progression." (PMID 27906180, 2016). "Taken together, our study demonstrates novel regulatory circuits involving miR-148a-3p/ERBB3/AKT2/c-myc and DNMT1 that controls bladder cancer progression, which may be useful in the development of more effective therapies against bladder cancer." (PMID 27906180, 2016). "In addition, in bladder cancer cell J82 with down-regulated expression of CHAF1A, some down-regulated expression of several genes related to cell growth and proliferation were found, including STAT2, STAT6, AKT2, IRS1 and SOX4." (PMID 37575547, 2023).
bladder cancer (continued). "However, AKT2 expression pattern in bladder cancer tissues was similar to that in adjacent non-tumor tissues (P>0.05)." (PMID 27906180, 2016).